IL10 (interleukin 10)
Diseases named in the same sentence as IL10 in open-access papers (continued):
Sharing a sentence is not in itself a finding about the gene and the disease.
tumor (continued). "Myeloid cell specific ablation of adenosine A2A receptor resulted in reduced melanoma tumor growth with significant increase in MHCII and IL-12 expression in TAMs with concomitant reduction of IL-10 expression in TAMs and MDCSs." (PMID 27886105, 2016). "The synthesis and secretion of cytokines and chemokines that are known to mediate MSCs' tumor-stimulating and immunosuppressive effects, i.e., IL-6, MCP-1 and IL-10, were down-regulated in lal−/− MSCs." (PMID 27531897, 2016). "Currently, it is unclear how the frequency of IL-10-expressing B cells is upregulated in the peripheral blood of HBV-related HCC patients and is further increased in tumor resections." (PMID 27136203, 2016). "In tumor-bearing mice, IL-2, IL-6, IL-12, TNF-α, and MCP-1 were up-regulated while IL-10 was down-regulated after cGAMP treatment." (PMID 26754564, 2016). "High levels of various soluble mediators were found in the peripheral blood and/or tumor microenvironment of HNSCC, such as VEGF, PGE2, TGF-β, IL-6, and IL-10." (PMID 27044404, 2016). "In breast cancer and lung adenocarcinoma, IL-10 and TGF-β1 have been confirmed to promote tumor growth through pathways including tumor migration and invasion." (PMID 27322426, 2016). "Here, the authors show that hepatocarcinoma cells drive the formation of semimature dendritic cells that in turn activate FcγRIIlow/− tumour B cells through the CD95L/CD95 axis, leading to the production of IL-10 and suppression of CD8 T cells." (PMID 27853178, 2016). "Following a response to MAPK pathway inhibition, there is an increase in PD-L1 expression on tumor cells and a higher lymphocytic infiltration (CD8/CD4), as well as, a decrease in Treg infiltration and immunosuppressive cytokines (IL6, IL10, VEGF)." (PMID 27447748, 2016). "Using B16-F10 tumor-bearing WT and hAAT+/+ mice, we performed IRP of tumor-bearing extremities and determined changes in VEGF, IL-12p40, IFNγ, and IL-10 transcription levels in the immediate inoculation site." (PMID 28003813, 2016). "Cytokines measurement revealed high levels of IFN-gamma, low levels of IL-10, and high IFN-gamma/IL-10 ratio in tumor environment of treated mice indicating initiation of Th1 response." (PMID 27927165, 2016). "Our PCR array data showed that both M1-related genes (Ccl2, Ccl3, Ccl4, Ccl5, Il12b, Il1b and Ccl1) and M2-related genes (Il10, Tgfb2 and Il1rn) were significantly upregulated in NM11-shsST2 tumours compared with NM11-shCont tumours." (PMID 27882929, 2016). "Administration of anti-CD40L antibody blocked HCC tumor growth enhancement by Bregs in vivo, blocked enhancement of HCC cell proliferation by Bregs in vitro and decreased IL-10 and TGF-β1 secretion while promoting an increase of TNFα secretion." (PMID 27437104, 2016). "Another study reported that FoxP3−LAP+ TI Tregs isolated from tumour tissue exhibited potent in vitro suppressive activity mediated by TGF-β and IL-10, and were up to 50-fold more suppressive than ‘conventional' FoxP3+ Tregs." (PMID 26885615, 2016). "The expression levels of IL-10 and TGF-β in plasma and tumor tissue were higher in the NB-Ehigh group than in the NB-Elow group." (PMID 27322426, 2016). "Our results showed that 6 days of treatment with tumour homogenates induced M2 macrophage makers, CD163, IL-10 and MMP9 expression, as well as the expression of legumain in U937 cells." (PMID 27464733, 2016). "We show that tumor tissue can secrete Nrp-1 and VEGF to support its growth, and their production closely parallels the co-expression levels of IL-10 and TGF-β." (PMID 27075020, 2016). "Treg constitute an important fraction of tumor-infiltrating CD4+ T cells and inhibit tumor-reactive T cells either by direct cell contact or through TGF-β and IL-10 production." (PMID 28003994, 2016). "In summary, IL10 triggers positive feedback between JAK1 and Src to amplify the activity of STAT3, thus leading to tumor formation." (PMID 26956044, 2016).
tumor (continued). "We analyzed the serum levels of cytokines IL-6, IL-8, IL-10, IFN-γ, and TNF-α in tumor-bearing mice." (PMID 27764779, 2016). "In contrast, anti-inflammatory macrophages are high producers of anti-inflammatory mediators, such as IL-10 or TGF-β, and are mainly involved in extracellular matrix remodelling and immune suppression, being considered tumour promoters." (PMID 27513864, 2016). "Tumor and spleen-derived CD4+Foxp3+ Treg cells obtained from anti-TGF-β-treated IL-10−/− B16/F10 mice were significantly increased." (PMID 27075020, 2016). "We examined the correlation between IL-10-expressing B cells and CD4+ T cells in the resected tumor." (PMID 27136203, 2016). "Third, DCs differentiated from tumour-isolated monocytes (TMO-DCs) also displayed semimature phenotype as that exhibited by TDCs, and that they markedly induced B-cell activation and IL-10 production." (PMID 27853178, 2016). "Therefore, the CSF IL-10 level may reflect the tumor burden or an active disease state." (PMID 27924864, 2016). "Analysis of intracellular cytokine production was used to determine production of IFN, IL-2 and IFN- in tumor-infiltrating CD8+ T and natural killer (NK) cells and IL-10 production by T regulatory cells." (PMID 27178315, 2016). "We found that a significantly higher frequencies of IL-10-expressing B cells and significantly lower frequencies of CD4+ cytotoxic T cells in the tumor, compared to their counterparts in peripheral blood." (PMID 27136203, 2016). "YPF resulted in the increased expression of IL-2 (p = 0.0498) but significantly downregulated the expression of TGF-β, IDO, and IL-10, suggesting that YPF can result in the downregulation of TGF-β, IDO, and IL-10 in tumor microenvironment." (PMID 27034590, 2016). "Surprisingly, the Nrp-1-expressing CD4+ T cells obtained from the tumor and TDLN were strongly up-regulated in IL10−/− B16/F10 mice, with the exception of the spleen." (PMID 27075020, 2016). "Constitutive expression of IL-6, TGF-β1, IL-17A, VEGF, IL-4, IL-10 and IDO by tumor cells as a major component of immune escape and immunosuppression in human EOC." (PMID 27118139, 2016). "M2 macrophages secrete immune-suppressive cytokines such as IL-10 and TGF-β, promote T regulatory (Treg) cell differentiation and aid in tumor progression." (PMID 26967393, 2016). "The milieu created by the tumor and the myeloid cells differentiates naive CD4 T cells into FoxP3+ T regulatory cells that are also producers of IL10 and TGFβ." (PMID 26561829, 2015). "For example, IL10, LIF and IL1RA were similarly regulated in GBM tumor at transcript level as measured by RNase protection assay." (PMID 26390214, 2015). "Tumor cells secret TGF-β and IL-10, which are the most well-known immunosuppressive cytokines, to escape immune surveillance." (PMID 25992978, 2015). "Recent data suggest that macrophages and DC binding to PS can stimulate IL-10 and TGF-B-dependent immunosuppressive signals and help induce immune tolerance in the tumor microenvironment." (PMID 25826750, 2015). "We found that the percentages of CD14+CD169+IL-10+ M2-like circulating monocytes and TIMs were significantly higher in CRC patients than in the HC or the non-tumor patients following in vitro activation." (PMID 26509874, 2015). "Live tumor cells are shown to produce immunosuppressive cytokines such as IL-10 and TGF-β to hinder anti-tumor T cell responses and promote T regulatory (Treg) cell functions." (PMID 26343191, 2015). "The tumor secretes TGFβ vascular endothelial growth factor (VEGF), prostaglandin E2 (PGE2), and IL-10 that suppress T cell proliferation and cytotoxic responses." (PMID 25972872, 2015). "Their suppressive function is mediated by a few different mechanisms such as production of suppressive cytokines including IL-10 and TGF-β, depletion of arginine in the tumor or production of reactive oxygen species (ROS)." (PMID 26648934, 2015).
tumor (continued). "M1 toward M2 polarization is favored by increase in IL10 and reduction in IL12, which lead to reduced Th1 activity and tumor immune evasion, along with angiogenesis and tumor promotion." (PMID 25607954, 2015). "The research study showed that tumor-activated liver sinusoidal endothelial cells (LSECs) affect liver sinusoidal lymphocytes (LSLs) anti-tumor cytotoxicity and IFN-γ/IL-10 secretion through MR-dependent mechanisms." (PMID 26379663, 2015). "Other immunosuppressive factors like IL-10 and TGF-β are secreted by tumor cells, editing the tumor microenvironment to attenuate immune response." (PMID 26487966, 2015). "The immunosuppressive cytokines, such as interleukin 10 (IL-10) and transforming growth factor β (TGF-β) are secreted by tumor cells and inhibit the maturation of DCs and effector T cell function through the induction of regulatory T cells (Tregs)." (PMID 26327508, 2015). "Daily oral intake of mushroom beta-glucan in tumor-bearing mice increases the amounts of IL-12 and IFN-γ gene expression and lowers the gene expression of IL-6, IL-10, COX-2, and TGF-β in tumor tissues of tumor-bearing mice." (PMID 26167490, 2015). "In contrast, M2, the alternatively activated MΦ/Mo induced by anti-inflammatory cytokines, produce high levels of IL-10 and low levels of IL-12, and thus inhibit development of Th1 cells and CTL responses and facilitate tumor progression." (PMID 26579227, 2015). "As a defense, tumor cells secrete immunosuppressive factors and express certain proteins, such as TGF-β, IL-10 and VEGF, which negatively regulate the anti-tumor immune response and promote tumor growth." (PMID 25785839, 2015). "If immature DCs maintain their tolerogenic profile induced by tumor cells, as indicated by the increased IL-10 expression in our in vitro studies, this could lead to the induction of regulatory T cells, and/or T-helper (Th)-2 responses instead of Th-1 anti-tumor immune responses." (PMID 25886502, 2015). "M1 macrophages are pro-inflammatory in function, they secrete IFN-γ, IL-12 and TNF-α, and therefore effectively suppress tumor growth while M2 like TAMs secrete TGF-β, IL-10, IL-17, IL-23, VEGF, and FGF2, promote angiogenesis and tumor progression." (PMID 26198107, 2015). "They produce high levels of IL-10, TGF-β, CCL-1, and CCL-22 and low levels of IL-12 and promote tumour growth and metastasis." (PMID 25588705, 2015). "To further confirm this characteristic in tumor tissues, we performed fluorescence labeling and confocal microscopy analyses of CD19+IL-10+B cells were performed in tumors." (PMID 26378021, 2015). "Dectin-1 engagement is apparent to up-regulate costimulatory molecules such as CD80, produce TNF-α, IL-6, IL-2, IL-10, IL-12, and IL-23, and elicit potent CTL responses that protect mice from tumor challenge." (PMID 26379663, 2015). "TAMs can kill tumor cells following activation by IL-2, IFN-γ and IL-12, but they also produce IL-10, which inhibits the CTL-mediated antitumor response and therefore promotes tumor progression." (PMID 25663851, 2015). "In the tumor microenvironment, tumor cell-derived factors (e.g., TGF-β1, IL-10, IL-6) induce the polarization of macrophages into tumor-associated macrophages (TAMs) with pro- or anti-tumor phenotypes." (PMID 31557983, 2015). "Some examples of such process are induction of specific tolerance to tumor antigens, TGF-β and/or IL-10 production, down-regulation of MHC molecules, or up-regulation of FasL expression." (PMID 26379663, 2015). "Ectopic IL-10 delivery during the T-cell stimulation phase further increased the levels of IFN-γ production and hindered tumor growth." (PMID 26217588, 2015). "Tumor cells by themselves secrete TGF-beta, IL-10, VEGF, PGE2 that induce DCs to secrete more TGF-beta contributing to the conversion of CD4(+) T cells to Treg phenotype, enhancing the cellular immune suppression once more." (PMID 32309563, 2015).
tumor (continued). "Our study found that daily oral intake of celecoxib or mushroom beta-glucan from Antrodia camphorata can decrease the gene expression of IL-6, IL-10, COX-2, and TGF-β and further decreases the proportion of M2 macrophages in tumor-bearing mice." (PMID 26167490, 2015). "In the tumor tissues biopsies analysed, IL-4, IL-10, and TGF-β1 were the main cytokines expressed and their expression was maintained during growth of the tumor." (PMID 24808638, 2014). "Interestingly, elevated levels of IL-10 are frequently detected in the serum of cancer patients and correlate with poor prognosis, suggesting that IL-10 may contribute to immune suppression and protect tumor cells from cytotoxic T lymphocytes by down-regulation of class I and class II MHC." (PMID 24520416, 2014). "Recent studies have shown that several potential molecules and pathways, such as suppressive cytokines IL-10 and TGF-β, as well as the inhibitor molecules PD-1 and IDO, are utilized by tumor cells to induce immunosuppression and immune escape." (PMID 25231413, 2014). "Tumor cells can indeed secrete immunosuppressive molecules, including vascular endothelial growth factor (VEGF), IL-10 and transforming growth factor-β (TGF-β)." (PMID 25505783, 2014). "IL-27 promotes the secretion of IL-10 and IFN- by CD4+ T cells, and we assume that these cytokines have the same effect on tumor rejection as those secreted by CD8+ T cells." (PMID 24633175, 2014). "One mechanism to promote these immunosuppressive populations is the secretion by tumor cells of immunosuppressive products such as prostaglandin E2 (PGE2), VEGF, IL-10, and TGF-β that favor Treg induction and expansion." (PMID 24734218, 2014). "On the other hand, we found FAS, FPR1, ID1, IL10, PCGF2, VDR among downregulated proteins: all are involved in tumor immune-escape through induction of apoptosis and anti-inflammatory activities." (PMID 25594007, 2014). "TAMs contribute to tumor progression by releasing a variety of cytokines, such as VEGF, PDGF and IL-10." (PMID 24885636, 2014). "Whilst there is clear evidence that IL-10 is immunosuppressive and protumorigenic, there is also new contradictory evidence that IL-10 can enhance apoptosis and downregulate VEGF, TNF-α, and IL6 production by TAMs to suppress angiogenesis and tumor growth." (PMID 24955376, 2014). "However, tumor associated dendritic cells (TADCs), which infiltrate neoplastic tissues in response to tumor-derived chemokines, are functionally defective as they have an immature phenotype because of the immunosuppressive cytokines in the tumor microenvironment, such as TGF-β and IL-10." (PMID 24578639, 2014). "HPV+ tumor cells themselves express IL-10 and TGF-β1 and this modulates tumor cell proliferation, affects the local immune response, and generates an immunosuppressive state." (PMID 24808638, 2014). "In contrast, activated M2 macrophages express high levels of the scavenger receptor (SR), the mannose receptor (MR), IL-10 and TGF-β, which primarily enable macrophages to function in tissue remodeling, immune suppression and tumor progression." (PMID 25198511, 2014). "For instance, TGF-β VEGF and IL-10 expressions are regulated by STAT3; furthermore, these proteins insure the continuance of STAT3 activation in immunosuppressive tumor microenvironment." (PMID 25333973, 2014). "In primary tumor tissues, ILT4 or IL-10 was expressed in the cell membrane, cytoplasm, or both; the positive rate of ILT4 and IL-10 expression was 60.7% (71/117) and 80.34% (94/117), respectively." (PMID 24762057, 2014). "The developing tumor progressively compromises the immune system by tumor related/derived factors, which include TGF-β, IL-10, PGE2, and gangliosides." (PMID 25248151, 2014). "The production of both IL-10 and TGF-β suppresses anti-tumor activities of the immune system allowing tumor cells to avoid destruction by immune cells." (PMID 26932379, 2014).
tumor (continued). "Unfortunately, as tumors actively fight to suppress effector cell function by producing immunosuppressive factors such as IL-10, TGFß, and VEGF, effective tumor eradication is rarely successful." (PMID 25365237, 2014). "In the present study we detected a Th2/Th3-type cytokine expression profile (IL-10, IL-4 and TGF-β1) in an HPV16-positive murine tumor model and found that this profile changes following treatment with the IL-12 gene." (PMID 24808638, 2014). "Finally, the anti-inflammatory cytokine IL-10 may also contribute to tumor growth." (PMID 24901008, 2014). "Tumor-derived Ang-2, for example, increases TEM IL-10 production, while suppressing IL-12, together directly and indirectly hindering tumor rejection by effector T cells." (PMID 24404127, 2014). "Soluble mediators released by tumor cells can directly inhibit CTLs, which include TGFβ, IL-10, PGE2, histamine, hydrogen peroxide, and adenosine, in addition to the hypoxic conditions and low extracellular pH that characterize the tumor environment." (PMID 24967214, 2014). "Collectively, these data strongly suggest that within the tumor microenvironment, some mouse γδ T cell populations express IL-4, IL-10, and TGF-β and inhibit the anti-tumor immune response." (PMID 25538706, 2014). "DCs differentiated in the presence of adenosine express higher levels of VEGF, IL-6, IL-8, IL-10, COX2, TGFβ, and indoleamine 2,3-dioxygenase (IDO), thus sustaining tumor angiogenesis." (PMID 25072019, 2014). "They found that IL-27 significantly enhances the survival of activated tumor antigen specific CD8+ T cells in vitro and in vivo, and induces IL-10 upregulation in these T cells." (PMID 24633175, 2014). "Existing data suggest that some cytokines, such as IL-6, IL-10 and VEGF, play an important role in KSHV-related cancer pathogenesis, including the promotion of tumor cell growth, angiogenesis, and the suppression of T cell activation." (PMID 24587336, 2014). "We recall, as noted in the Introduction, that for wild type mouse, both CD4+ and CD8+ T cells produce IL-10 and IFN- and we assume that IL-10 secreted by CD4+ T cells has the same tumor rejection quality as the IL-10 secreted by CD8+ T cells." (PMID 24633175, 2014). "Among the most downregulated proteins, we found several confirmed or candidate tumour suppressor genes (eg, ID1, FAS, FPR1, IL10, PCGF2, VDR)." (PMID 25594007, 2014). "The model involves a dynamic network which includes tumor cells, CD8+ T cells and cytokines Interleukin-27, Interleukin-10 and Interferon-." (PMID 24633175, 2014). "Recent studies implicate myeloid derived suppressor cells (MDSC) in the induction of CD8+ T cell tolerance in tumor-bearing hosts and that appear to be recruited by tumor-derived soluble factors such as TGF-ß1, IL-10, VEGF, GM-CSF, IL-6 and prostaglandin E2." (PMID 24457057, 2014). "Tumor growth is also favored by proinflammatory cytokines that stimulate cell proliferation and reduce apoptosis, while anti-inflammatory cytokines, such as IL-10 and TGF-β, contribute to tumor immune evasion." (PMID 24901008, 2014). "IL-10, along with TNF-α, autocrinally stimulated the expression of B7-H1 on macrophage surface, impairing CD8+ T cell activity and supporting tumor immune escape." (PMID 23533994, 2013). "This combination therapy not only altered the profiles of Tregs, CD4+ T cells and CD8+ T cells but also influenced the cytokines (IL-12, IFN-γ, IL-10 and TGF-β1) at tumor sites." (PMID 24304581, 2013). "We showed that Tr1 proliferation as well as IL-10 and TGF-β production responsible for their suppressor functions were dependent on COX-2 expression in tumor cells." (PMID 23898333, 2013). "Tumor-associated macrophages release inflammatory mediators that stimulate tumor angiogenesis and lymphangiogenesis, and produce cytokines, including transforming growth factor (TGF) β and IL-10, that can directly suppress immune responses." (PMID 23987103, 2013).